SMAD4 (SMAD family member 4)
Diseases named in the same sentence as SMAD4 in open-access papers (continued):
Sharing a sentence is not in itself a finding about the gene and the disease.
colon carcinoma (continued). "Whether TGFβ actively promotes cancer progression in Smad4-deficient colon cancers is not well established." (PMID 33990575, 2021). "APC, SMAD4 (SMAD family member 4), NF1 (neurofibromin 1), ARID5B, NCOR1 (nuclear receptor co-repressor 1), IGFR1R (insulin like growth factor 1 receptor) and GNAS (GNAS complex locus) were the most often mutated genes in patient-derived colon cancer cells, YUMC-C1 and YUMC-C2." (PMID 33050525, 2020). "Direct at miR-144/SMAD4 pathway may provide a novel therapy for colon cancer patients." (PMID 30745456, 2019). "Moreover, SMAD4 level, both in mRNA and protein, was obviously elevated in colon cancer tissues." (PMID 30745456, 2019). "To test this hypothesis, we assessed whether activin and/or TGFβ led to PI3K activation via primary receptor association with the p85 regulatory subunit of PI3K and the subsequent downstream increase in phosphorylation of Akt in SMAD4 wild type and null colon cancer cell lines." (PMID 26497569, 2015). "Within the top 20 TFs that showed high correlation between their own CNV and expression, we observed known colon cancer drivers ZNF703 and SMAD4, as well as IRF2 and GATA6, whose DNA aberrations are likely oncogenic." (PMID 41114645, 2025). "SMAD family member 4 (SMAD4) is a critical component of the TGF-β pathway that acts as a tumor suppressor in several cancers, including pancreatic, bile duct and colon cancer." (PMID 37407839, 2023). "To exclude Smad3/Smad4-mediated transcriptional induction of ID1, we used Smad4-null SW620 and HT29 colon cancer cells." (PMID 33990575, 2021). "The results documented that the sensitivity of LoVo colon cancer cells to DDP, oxaliplatin, 5-Fu, and paclitaxel was obviously increased, P-gp expression was significantly decreased, and SMAD4 expression was clearly enhanced after knocking down OLR1." (PMID 34921134, 2021). "Previous studies revealed that in colon cancer, the activation of TGF-β signaling induced ERK and P38 signaling and stimulated angiogenesis by VEGF upregulation when SMAD4 was knocked down." (PMID 33672900, 2021). "Some studies have shown that the low expression of SMAD4 is believed to inhibit cell proliferation, metastasis and EMT, such as in colon cancer and esophageal squamous cell carcinoma." (PMID 33292220, 2020). "After TGF-β treatment, activin secretion was increased both in SMAD4 wild-type FET and SMAD4 null SW480 colon cancer cells." (PMID 28717230, 2017). "Evidence has shown that SMAD4 can inhibit the expression of VEGF-C and, therefore, inhibit lymphangiogenesis in colon cancer." (PMID 29065177, 2017). "In this network diagram, many genes were closely related with colon cancer progression such as PTEN, STAT3, FOXO1, and SMAD4." (PMID 28938919, 2017). "The FET colon cancer cells have functional activin signaling and the SW480 colon cancer cells have functional ACVR2, but lack SMAD4." (PMID 28418896, 2017).
colon carcinoma (continued). "In summary, we demonstrated for the first time that miR-27a was a key regulator of lymphangiogenesis in human colon cancer and that it functioned via the TGF-β-SMAD4 signaling pathway." (PMID 29065177, 2017). "The correlation of USP3, SMAD4 and miR-224 was also verified in GSE29623, a GEO dataset containing mRNA and miRNA expression profiles of 65 colon cancer specimens." (PMID 28655924, 2017). "Colon cancer cells treated with doxorubicin underwent EMT, and inhibition of TGFβ/Smad4 signaling pathway by the downregulation of Smad4 reversed doxorubicin-induced EMT." (PMID 27455225, 2016). "Using ACVR2A/TGFBR2 wild type FET colon cancer cells, FET with SMAD4 knockdown, and the SMAD4-null colon cancer cell line SW480, we found a SMAD4-independent increase in pAkt Ser473 after activin treatment compared to control and TGFβ treatment." (PMID 26497569, 2015). "Therefore, downregulation of Smad4, or treatment with inhibitors to inhibit TGFβ signaling or Smad2 and/or Smad3 phosphorylation, combined with Dox may be a potential novel strategy with which to treat colon cancer." (PMID 25684678, 2015). "Although TGF-beta signaling acts as a tumor suppressor in a subset of colon cancer cells (i.e. FET, GEO and CBS, etc) that express wild type Smad4, Smad4-independent TGF-beta signaling has been shown to promote colon cancer metastasis." (PMID 23536895, 2013). "By studying the same orthologous genes in colon tumors from humans and the CRC mouse model B6 ApcMin/+, we found that bona fide cancer genes APC and SMAD4 were disrupted in both species." (PMID 20707908, 2010). "Various molecular and biological differences have been reported between colon and rectal cancers, and SMAD4 may play a more prominent role in the development of colon cancer in EoCRC, potentially through dysregulation of the TGF-β/SMAD4 signaling pathway." (PMID 41075061, 2025). "Furthermore, consistent with the fact that the miR-183/96/182 cluster directly targets SMAD4 and FOXO3, they observed a significant increase in the levels of SMAD4 and FOXO3 following avenanthramide C treatment in colon cancer cells." (PMID 39334758, 2024). "Furthermore, we present novel data on the positive prognostic value of stromal RUNX3, SMAD4, and IRS-1 in colon cancer." (PMID 36900240, 2023). "Since motility in colon cancer cells has been associated with the activation of transforming growth factor TGFβ signaling, we used the SW480 colon cancer cell line, which lacks SMAD4 expression as negative control." (PMID 34885136, 2021). "Therefore, in colon cancer cells, TGFβ stabilizes p21 via MEK/ERK in a SMAD4-dependent manner resulting in upregulation of p21." (PMID 26497569, 2015). "In contrast, neither ligand was growth suppressive in the absence of SMAD4 in ACVR2/TGFBR2 wild type/SMAD4-null SW480 colon cancer cells or following SMAD4 knockdown in SMAD4 wild type FET cells." (PMID 22761777, 2012). "We were able to show that re-expression of Smad4 in these colon carcinoma cells was not sufficient to restore TGF-β responsiveness." (PMID 21492476, 2011). "The expression ratio of transcripts SMAD4-209 and SMAD4-213 was suggested as a biomarker candidate for colon cancer detection, while another study proposed the CD81-215 transcript as a long non-coding RNA of stromal origin with a potential tumor-promoting role in colon cancer." (PMID 41050078, 2025).
colon carcinoma (continued). "Furthermore, the sensitivity of LoVo colon cancer cells to DDP, oxaliplatin, 5-Fu, and paclitaxel was distinctly enhanced, P-gp expression was authentically declined, and SMAD4 expression was noticeably augmented subsequent to OLR1 knockdown, which was reversed by further overexpressing c-MYC." (PMID 34921134, 2021). "Mothers against decapentaplegic homolog 4 (SMAD4) is the central mediator of TGF-β signaling; its mutations have been identified in CRC and it is associated mainly with colon cancer (rather than rectal cancer), female sex, and shorter OS than wt SMAD4 CRC patients (mOS 29 months vs. 56 months)." (PMID 32413973, 2020). "As expected, this increase in activity is sensitive to NFkB inhibition by wtNBD peptides suggesting that inhibition of NFkB activation may be an effective therapeutic approach for colon cancers regardless of SMAD4 status." (PMID 28418896, 2017). "MMP7 has been shown to be important for accelerating cancer invasion and metastasis in multiple tissues, but does not seem to be necessary for invasion or fibrosis of colon cancer, in which Smad4-dependent transforming-growth-factor (TGF)-β family signaling is blocked." (PMID 25424420, 2014). "In this study we demonstrated that the microRNA-130a/301a/454 family is up-regulated in colon cancer tissues compared to paired adjacent normal mucosa, which share the same 3′-untranslational region (3′-UTR) binding seed sequence and are predicated to target Smad4." (PMID 23393589, 2013). "Of note, these results were obtained in HT29 colon carcinoma cells, which are Smad4-negative." (PMID 18664273, 2008). "In colon cancer, this pathway is non-dominant and activin preferentially downregulates p21 via PI3K/Akt in a SMAD4-independent fashion." (PMID 26497569, 2015).
juvenile polyposis syndrome (137 papers, 2008 to 2026). Juvenile gastrointestinal polyposis (JIP) is a rare condition characterized by the presence of juvenile hamartomatous polyps in the gastrointestinal (GI) tract. "Mutations in mothers against decapentaplegic homolog 4 (SMAD4), associated with juvenile polyposis, and in growth differentiation factor 2 (GDF2, also known as BMP-9), are much rarer." (PMID 40007589, 2025). "Loss of function mutations within MADH4 (Mothers against decapentaplegic homolog 4, the gene encoding SMAD4), are responsible for the combined syndrome juvenile polyposis-HHT overlap (JP-HHT) and have also been implicated in bAVM formation." (PMID 39899215, 2025). "SMAD4 (SMAD family member 4): This gene is associated with a rare form of HHT that can present with juvenile polyposis syndrome." (PMID 40993782, 2025). "SMAD4 is one of the commonly mutated somatic drivers of CRC49 and germline mutations in SMAD4 predispose to juvenile polyposis syndrome." (PMID 39654522, 2025). "The combined phenotype occurs because SMAD4 mediates signalling through the BMPR1A receptor implicated in juvenile polyposis (JP, OMIM174900), and ACVRL1/Endoglin signalling involved in Hereditary Haemorrhagic Telangiectasia (HHT, OMIM187300 &600376)." (PMID 38627541, 2024). "SMAD4 pathogenic variants are also associated with syndromic conditions (Juvenile polyposis syndrome and Myhre syndrome)." (PMID 39596629, 2024). "Pathogenic SMAD4 variants are associated with various diseases, such as cancer and juvenile polyposis syndrome (JPS)." (PMID 39589938, 2024). "In particular, SMAD4 is frequently mutated in pancreatic cancer, colorectal cancer, and juvenile polyposis, where its dysfunction leads to the formation of gastrointestinal polyps and increases the risk of malignancies." (PMID 39589938, 2024). "Identification of SMAD4 mutations in a subset of HHT patients having juvenile polyposis increased the possibility that HHT is a disease caused by defects in the signaling of a TGF-β family member(s)." (PMID 36348215, 2023). "Pathogenic/likely pathogenic variants in SMAD4 (encoding the transcription factor Smad4) have been described in less than 2% of the HHT population associated with juvenile polyposis/HHT overlap syndrome." (PMID 36981042, 2023). "Juvenile polyposis (JP) is a rare disease known to be associated with mutations either in SMAD4/BMPR1A." (PMID 35928693, 2022). "HHT patients with Smad4 mutation, a colonoscopy must be offered since its association with juvenile polyposis." (PMID 36079173, 2022). "Presence of germ line mutations in MADH4 of juvenile polyposis families further supports that the Smad4 act as a tumor suppressor." (PMID 35295334, 2022). "Strong nuclear expression of SMAD4, even under the presence of genetic alterations, seems to be closely associated with dysplastic polyps in juvenile polyposis (JP)." (PMID 35928693, 2022). "Juvenile polyposis syndrome (JPS) is also an inherited autosomal dominant syndrome driven by mutations in either BMPR1A (MIM: 601299) or SMAD4 (MIM: 600993)." (PMID 36551963, 2022). "One patient was a carrier for SMAD4 pathogenic variant c.455‐2A > G, which is associated with juvenile polyposis syndrome." (PMID 35128723, 2022). "Mutations or deletions in this gene have been shown to result in the development of juvenile polyposis syndrome, whereas weak expression of SMAD4 is known to associate with poor survival in patients with bowel cancer." (PMID 35154239, 2021). "Disease-causing variants in the MADH4 gene (OMIM 60093), which encodes SMAD4 and is located on chromosome 18q, have been found in patients with juvenile polyposis and HHT symptoms." (PMID 32962750, 2020).
juvenile polyposis syndrome (continued). "Germline mutations in SMAD4 cause juvenile polyposis syndrome (JPS) with an autosomal dominantly inherited predisposition to multiple gastrointestinal polyps and cancer." (PMID 30730996, 2019). "One patient with mutations in both ENG and ACVRL1 genes was identified, as were two SMAD4-mutated patients suffering from the overlapping juvenile polyposis-HHT syndrome." (PMID 30251589, 2018). "The risk of gastric cancer in patients with juvenile polyposis was reported to be approximately 11–21%, with a higher risk in patients with a SMAD4 germline mutation." (PMID 30043121, 2018). "Some patients have a family history of juvenile polyposis with an autosomal dominant pattern of inheritance, and SMAD4 and BMPR1A have recently been identified as causative genes for juvenile polyposis." (PMID 30043121, 2018). "The polyps in proband 344 and affected sibling 447 of family 1 are adenomas with just a few mixed polyps documented in 447; hence it is unlikely that the SMAD4 gene (responsible for juvenile polyposis) is disease-causing." (PMID 28306719, 2017). "It is now clear that the spectrum of SMAD4 mutations in patients or families described as having Juvenile Polyposis Syndrome (JPS) alone are almost identical to those with JP/HHT combined." (PMID 25674101, 2015). "Mutations in ENG were identified in 31 patients (55%), mutations in ACVRL1 were identified in 17 patients (30%), and one patient had a mutation in SMAD4 and presented with juvenile polyposis." (PMID 24603803, 2014). "Mutations in three genes have been found to be responsible for HHT: the endoglin (ENG) gene on chromosome 9, the activin-receptor-like kinase 1 (ACVRL1) gene on chromosome 12, and the SMAD4 gene on chromosome 18 (mutations also lead to juvenile polyposis)." (PMID 24603803, 2014). "Mutations in two different genes (BMPR1A and SMAD4) are known to cause juvenile polyposis syndrome in 20% of cases each." (PMID 18826596, 2008). "Results of the immunohistochemical analysis of intestinal polyps from Juvenile Polyposis syndrome patients carrying established SMAD4 germline mutations." (PMID 19014666, 2008). "Additionally, we have highlighted the role of genetic background on juvenile polyposis syndrome (JPS) development in Smad4-deficient mice, revealing line-specific variations in intestinal polyp development." (PMID 39596873, 2024). "These include APC for familial adenomatous polyposis (FAP); BMPR1A and SMAD4 for Juvenile Polyposis Syndrome (JPS); MUTYH for MUTYH-associated polyposis; PTEN for PTEN tumor/hamartoma syndrome (or Cowden syndrome/Bannayan–Riley–Ruvalcaba syndrome); and STK11 for Peutz–Jeghers syndrome." (PMID 37965459, 2023). "SMAD4 mutations in patients with juvenile polyposis syndrome may also develop hereditary hemorrhagic telangiectasia, which results in abnormal vascular structures." (PMID 36267157, 2022). "Genetic diagnosis is based on the identification of a mutation in the transforming growth factor-beta (TGF-β) signaling pathway genes: Endoglin (ENG), activin receptor-like kinase 1 (ACVRL 1), or SMAD4 characterized by the juvenile polyposis syndrome (JPS) usually associated with HHT." (PMID 31971937, 2020). "Juvenile polyposis syndrome, the appearance of multiple hamartomatous polyps in the gastrointestinal tract associated with the increased risk of adenocarcinoma, is caused by mutations in SMAD4 gene." (PMID 31238579, 2019). "Interestingly, we have detected pathogenic SMAD4 somatic missense variants previously reported in cases of juvenile polyposis syndrome in 6 adult CRC patients." (PMID 27146902, 2016). "Finally, some SMAD4 mutations can cause a syndrome comprising both juvenile polyposis and HHT phenotypes while BMP9 mutations have been linked to vascular malformations that have phenotypic overlap with HHT." (PMID 25763012, 2015). "Germline mutations in SMAD4/DPC4 have also been identified in certain types of juvenile polyposis." (PMID 24625091, 2014).